ALK (ALK receptor tyrosine kinase)
Diseases named in the same sentence as ALK in open-access papers (continued):
Sharing a sentence is not in itself a finding about the gene and the disease.
tumor (continued). "Anaplastic Lymphoma Kinase (ALK) is a receptor tyrosine kinase aberrantlyexpressed in a variety of tumor types, most notably in Anaplastic Large CellLymphoma (ALCL) where a chromosomal translocation generates the oncogenic fusionprotein, Nucleophosmin-ALK (NPM-ALK)." (PMID 21423761, 2011). "We established that this new class of BPs was the more potent among the current non N-BPs since clodronate, even used at 1600 mg twice daily during several weeks (as compared to BP7033 ALK corresponding human dose of 770 mg twice a week during only 2 weeks) failed to reduce primary tumor growth." (PMID 19262688, 2009). "However, another study has reported that ALK positivity might indicate a good prognosis, while patients with gene rearrangements involving both RAN binding protein 2 (RanBP2) and ALK exhibit a higher tumor recurrence rate and a relatively poor prognosis." (PMID 40224630, 2025). "Overall, alterations in EGFR and ALK genes are relatively rare in primary PLEC However, there may still be some special cases with EGFR or ALK gene alterations that interact with other factors or are related to individual differences of patients, tumor heterogeneity, or detective methods." (PMID 40881855, 2025). "Moreover, the 5-year results from the phase III NCT02220894 study highlighted the sustained efficacy of pembrolizumab as a first-line treatment for locally advanced or metastatic NSCLC without EGFR or ALK alterations in all PD-L1 tumor proportion score (TPS) groups compared to chemotherapy." (PMID 39199653, 2024). "Therefore, it is possible that an ALK vaccine could generate an anti-tumor response in patients who have the presence of these autoantibodies and may stimulate a tumor response in patients without them." (PMID 38835344, 2024). "However, there have been reports of ALK gene rearrangements, and ALK gene expression has been associated with local recurrence, suggesting that IMT is not the result of an inflammatory response but rather a tumor lesion." (PMID 39516994, 2024). "Although this mechanism has yet to be investigated in HGSC, elevated expression of ALK protein was reported in 28% of HGSC samples (independent of ALK mutation or gene rearrangement), providing one potential mechanism for MYCN up-regulation in the tumor microenvironment." (PMID 38748789, 2024). "However, the use of ALK inhibitors without sufficient consideration is controversial, because IAH1-ALK is a novel ALK fusion gene, and the ALK signal was negative as determined by the immunostaining of lymph node metastasis samples, suggesting primary tumor heterogeneity." (PMID 39781173, 2024). "Moreover, the tumor cells were negative for ALK overexpression." (PMID 35642345, 2023). "Patients who carried driver gene mutations (EGFR or BRAF mutations or ALK/ROS1 rearrangements), who received ICIs as neoadjuvant treatment or less than two cycles of ICIs, who were lost to follow-up, and who did not complete the tumor response assessment were excluded from the study." (PMID 37359565, 2023). "Therapies targeting several genes, including EGFR-TKI, ALK-TKIs, MET-TKIs, antiangiogenic therapy and immune-checkpoint inhibitors, were tested in patients with PSC, although given the rarity of the tumor type, large scale studies of any particular therapy may never be completed." (PMID 35592676, 2022). "Based on the data presented here, brigatinib possesses potent anti-tumor activity against NF2-deficient tumors via inhibition of multiple RTKs frequently activated in these tumors as well as blockade of several non-RTKs and serine-threonine kinases, but not ALK." (PMID 34264955, 2021). "In addition to expression in most CD4+CD25+ ATLL, CCR4 is expressed in approximately 30–65% of PTCL tumor cells, including high expression (~ 65%) in ALK-negative ALCL, variable expression (30–40%) in PTCL/NOS, AITL, and transformed MF, while rarely expressed in ENKTL or ALK-positive ALCL." (PMID 32448357, 2020).
tumor (continued). "Therefore, autoantibodies against ALK might not have direct anti-tumor activity but rather represent a surrogate marker for the ALK-specific T cell response." (PMID 29642597, 2018). "Hence, ALK rearrangement screening by fluorescence in situ hybridization (FISH) and/or immunohistochemistry (IHC) is not routinely performed in patients with Sq-LC, leading to inadequate identification of the molecular tumor subtype, which can affect decisions regarding the best treatment options." (PMID 29844868, 2018). "As well as disease stage, tumor genotype could also be an important determinant of culture success in these conditions: previous studies focus on biopsies and plural effusions from EGFR‐mutant/ALK‐positive tumors, while 7 of our 10 LUAD tumors were driven by mutant KRAS." (PMID 29569246, 2018). "Moreover, cells under hypoxic conditions induced by CoCl2 treatment showed a decrease in ALK expression, suggesting that non-hypoxic tumor microenvironment may be essential for maintaining ALK signaling activity." (PMID 28837676, 2017). "Those IMTs that are negative for ALK may not be true neoplasms and thus have a better prognosis." (PMID 24602144, 2014). "Moreover, ALK-F1174L expression, in mouse and zebrafish transgenic NB models, as well as in KI model, was not sufficient to initiate NB tumor formation in absence of MYCN co-expression or additional genetic alterations syntenic to that commonly found in human NB." (PMID 24947326, 2014). "Re-biopsy of relapsed metastatic tumor tissue showed newly emerged somatic mutations in both the KRAS and the EGFR gene, while the tumor cells still carried the original ALK rearrangement but without signs of ALK fusion gene amplification or secondary ALK mutations." (PMID 24279718, 2013). "Moreover, the ALK-positive staining was not seen in each primary tumor cell." (PMID 23341890, 2013). "However, no tumor positive for these two ALK fusions was found." (PMID 22140546, 2011). "The current paper addresses the safety of combining EGFR, ALK, and BRAF/MEK inhibitors with RT, regardless of (solid) tumor histology." (PMID 41759225, 2026). "Histopathological analysis favored a diagnosis of ALK-negative IMT, although the origin and differentiation trajectory of the tumor remained undetermined." (PMID 41560086, 2026). "In contrast to ALK+ ALCL, PTPN2 knockout did not significantly impair cell proliferation, induce apoptosis, or exhibit tumor‐promoting effects in FARAGE, RAJI, and JURKAT." (PMID 40734623, 2025). "Moreover, low tumor mitotic activity was associated with better prognosis in LUAD subgroups with EGFR mutations or pan-negative (no oncogenic alteration in genes including KRAS, EGFR, BRAF, ERBB2, PIK3CA, ALK, and ROS1) but not in those with KRAS or BRAF mutations." (PMID 41404730, 2025). "NGS is primarily applied in advanced non-squamous NSCLC, where tumor NGS testing is routinely recommended owing to the presence of numerous actionable genetic alterations, including EGFR, ALK, and ROS1, which can be targeted with specific therapies." (PMID 41515905, 2025). "In conclusion, we established an ALK-negative ALCL PDX and cell line model harbouring TP63 rearrangement that can not only recapitulate the original characteristics of the patient tumour, but also propagate in vivo." (PMID 40715645, 2025). "Morphologically, pc-ALCL resembles systemic ALK-negative ALCL, with over 75% of tumor cells expressing strong CD30 positivity." (PMID 40635103, 2025). "There is no anti-tumor effect from unconjugated CDX0239 alone and we did not observe evidence of phosphorylated ALK attenuation after treatment with CDX0239-PBD in NB-SD xenografts." (PMID 40813394, 2025). "Tumor cells exhibit large anaplastic morphology, are positive for CD30 and variably for pan–T-cell markers, but are negative for ALK expression." (PMID 40881873, 2025).
tumor (continued). "The tumor cells were diffusely CD34, ERG, and focally p63 reactive, while S100 protein, cytokeratin AE1/AE3, Pan-TRK, ALK, smooth muscle actin, and desmin were negative." (PMID 40878874, 2025). "We obtained tumor tissues and plasma samples from 48 patients with NSCLC without ALK rearrangement and 15 normal individuals." (PMID 40246819, 2025). "In this case, the tumour demonstrated ALK1 positivity with the absence of DUSP 22 or TP63 rearrangements, supporting the diagnosis of systemic ALK-positive ALCL." (PMID 41445989, 2025). "These tumor cells were positive for CD2, CD3, CD30 and p63, and negative for CD7, CD8, CD15, CD20, ALK and cytotoxic markers (TIA-1, granzyme B and perforin)." (PMID 40565334, 2025). "Currently, spread through air spaces (STAS) in stage I NSCLC is a risk factor significantly associated with poor prognosis for both OS and DFS, regardless of tumor size, and STAS is frequently observed in ALK-positive NSCLC." (PMID 39061248, 2024). "Testing ALK: ALK testing (clone D5F3 Ventana, Automat Benchmark) gave a negative result in tumor cells." (PMID 39064008, 2024). "When APH only involves the skin, the tumor characteristics are very similar to those of cutaneous JXG, and the difference between the two lies mainly in the presence or absence of an ALK translocation." (PMID 39867882, 2024). "Immunohistochemical stains were positive for PAX8, AE1/AE3, E-cadherin, CD10, and vimentin; the tumor was negative for CK7, CD117, racemase, ALK, and HMB45; the tumor showed focal, scattered staining for Melan-A and very weak cytoplasmic staining for CAIX." (PMID 39561576, 2024). "A study enrolled 92 ALK+ NSCLC patients, utilizing plasma cfDNA NGS for longitudinal monitoring, correlating the absence of baseline circulating tumor DNA (ctDNA) with longer PFS and OS." (PMID 38397899, 2024). "All tumour cells were negative for vimentin, CA9, CD10, P504s, CK20, TFE3, TFEB, HMB45, ALK and FOXI1." (PMID 36816543, 2023). "The main driver mutations of primary tumours with LM were determined by NGS, including EGFR L858R (10, 35.7%), EGFR 19del (6, 21.4%), EGFR L858R + MET amplification (1, 3.6%), EGFR L858R+S768I (1, 3.6%), ALK (2, 7.1%), ROS1 (1, 3.6%), negative (5, 17.9%), and unknown (2, 7.1%)." (PMID 38269023, 2023). "The relative incidence of CNS disease at first relapse/progression based on tumor histology was 5% (n = 4) for PTCL, not otherwise specified (NOS), 17% (n = 2) for ALK + ALCL, and 8% (n = 2) for ALK-negative ALCL (ALK- ALCL)." (PMID 36765882, 2023). "Tumor tissue from 49 patients with stage III or IV NSCLC who were without EGFR and ALK alterations were analyzed using targeted next-generation sequencing (NGS)." (PMID 37924135, 2023). "ALK-positive IMT of the breast is extremely rare and shows nonspecific imaging findings despite having the characteristics of low-grade neoplasms with recurrence, invasion, and metastatic potential." (PMID 37656266, 2023). "Atezolizumab, has recently been approved by the EMA as monotherapy for the “first-line treatment of adult patients with metastatic NSCLC with PD-L1 expression ≥ 50% TC or ≥ 10% tumour-infiltrating IC and who do not have EGFR mutant or ALK-positive”." (PMID 36647072, 2023). "The tumour cells express SMA and vimentin; partially express desmin, CD34, CD68 and ALK; and do not express CK or S100." (PMID 36855132, 2023). "Immunohistochemically, the tumor cells were positive for smooth muscle actin (SMA) and negative for cytokeratin, desmin, H-Caldesmon, CD34, S100, ALK, and β-catenin." (PMID 36741963, 2023). "No synergistic effect of the combination of ALK-TKI and PD-1 monoclonal antibody against tumor cells was observed using in vivo experiments." (PMID 37901223, 2023). "In the present study, we found that both pSTAT3-Y705 and -S727 were diffusely expressed by tumor cells in ALCL, irrespective of ALK status; though pSTAT3-Y705 was more specific and pSTAT3-S727 is more sensitive." (PMID 37388733, 2023).
tumor (continued). "For instance, Pembrolizumab has significantly improved the 5-year survival rate of advanced NSCLC patients and has been approved for first-line treatment in patients with PD-L1 tumor proportion score (TPS) ≥1% and without EGFR/ALK gene alterations." (PMID 38204755, 2023). "Previous studies suggest that ALK+ ALCLs and ALK+ ALCL cell lines, do not express TNF-α as a result of promoter methylation, thus preventing its proapoptotic function on tumor cells." (PMID 37810974, 2023). "One patient with tumor PD-L1 Tumor cell Proportion Score (TPS) expression >1%, without activating EGFR or ALK alterations, received a programmed death-1 (PD-1) blocker and had stable disease (SD)." (PMID 37342191, 2023). "Eligible patients had recorded programmed death-ligand 1 (PD-L1) tumor proportion score (TPS) and no known actionable EGFR/ALK/ROS1/BRAF genomic alteration." (PMID 35740512, 2022). "Since all patients with EIMS and 50% of the patients with IMT patients present with the activation of ALK, there is no doubt that IMT is a true neoplasm rather than a reaction to inflammation." (PMID 35327685, 2022). "The tumor cells were positive for CD23 and negative for CD79α, CD3, CD5, CD35, D2–40, and anaplastic lymphoma kinase (ALK)." (PMID 36484868, 2022). "All patients (23/23) presented with ALK negative tumors and 17% (4/23) exhibited a PDL1 of >50% tumor proportion score (TPS)." (PMID 35719971, 2022). "All patients had ALK negative tumors and a PDL1 tumor proportion score (TPS) of >50% was present in 17% of the tumors." (PMID 34208545, 2021). "Other tumor regions revealed some diffuse stainings of few TH+ positive cells with enlarged nuclei positive for MYCN, but negative for ALK (zoom 1), whereas other regions did not exhibit expression of TH, MYCN, and ALK (zoom 4)." (PMID 34493726, 2021). "Immunophenotypically, all tumour cells are positive for CD30 and negative for ALK and show variable expression of one or more T cell markers, such as CD3 and CD4." (PMID 33131026, 2021). "In ALCL, pre-clinical models have shown a positive correlation between PD-L1 expression in the tumor cells and TAMs in ALK-positive ALCL and conversely, a negative correlation in ALK-negative ALCL." (PMID 33806977, 2021). "In general, sALCL is an 18F-FDG avid tumor although, the SUV is different between ALK-positive and ALK-negative sALCL." (PMID 34441322, 2021). "The tumor cells were negative for CD117, DOG1, CD34, S100, β-catenin, STAT-6, and ALK that played important roles in differential diagnosis." (PMID 34516510, 2021). "Immunoreactivity for ALK and ROS1 resulted negative in both component, in primitive tumor and in lymph nodal metastasis." (PMID 34926584, 2021). "In a recent study blocking ALK and IGFR1 receptors together with the CT-707 drug, which is one of the FAK (focal adhesion kinase) inhibitors, significantly inhibited tumor growth without obvious side effects." (PMID 32876329, 2021). "Currently, when a tumor progresses, clinicians ask themselves if it is necessary or not to look for mechanisms of resistance to TKI that target ALK." (PMID 33467720, 2021). "Herein, we present a 58-year-old lady with advanced non-small cell lung cancer (NSCLC) ALK-negative, EGFR wild, and PD-L1 immune histochemistry (IHC) strongly positive in 95% of tumor cells, on ongoing treatment with Pembrolizumab as a first-line monotherapy." (PMID 33070259, 2021). "The STALKLUNG01 trial was designed to detect ALK gene rearrangements in CTCs, allowing patients with inoperable NSCLC to benefit from crizotinib treatment in instances when tumour biopsy is not feasible." (PMID 33652649, 2021). "No immunoreactivity for ALK and ROS1 with PD-L1 TPS of >50% were documented in the lower lobe neoplasia." (PMID 34926584, 2021). "FDA approval is for patients with PD-L1 stained ≥ 50% of tumor cells, or PD-L1 stained tumor-infiltrating immune cells covering ≥ 10% of the tumor area, with no EGFR or ALK genomic tumor aberrations." (PMID 33171686, 2020).
tumor (continued). "Additional genetic testing revealed the patient was negative for ALK fluorescence in situ hybridization, ROS1, BRAF, and EGFR and PD-L1 22C3 IHC with Tumor Proportion Score (TPS) of <1%." (PMID 33101670, 2020). "The stellate tumor cells in IMT are immunophenotypically positive for SMA, desmin and ALK, which are negative in PPMS." (PMID 32039736, 2020). "In the database of the Tumor Center Regensburg, we detected twelve cases of CD30-positive and ALK-negative ALCL outside the breast tissue between 2002 and 2018." (PMID 32344893, 2020). "Immunohistochemistry study revealed that the tumor cells were positive for CD4 and CD30, and were negative for cytokeratin, CD3, CD20, CD68, CD163, lysozyme, ALK, S-100, and desmin." (PMID 32547956, 2020). "Additional genetic testing revealed the patient was negative for EGFR, ALK fluorescence in situ hybridization, ROS1, BRAF, and PD-L1 22C3 IHC with Tumor Proportion Score (TPS) was less than 1%." (PMID 33101670, 2020). "The tumor cells were positive for Trk and SMA, but negative for S100, CD34, ALK, CD10, desmin, myogenin, CD99, CD56, CK, EMA, and STAT6." (PMID 32957984, 2020). "These particular tumours have expression of CD30 and are negative for Anaplastic Lymphoma Kinase (ALK)." (PMID 32550034, 2020). "Molecular analyses for all patients were negative for EGFR and ALK aberrations, one patient had a MET‐amplified tumor and two patients had high TMB." (PMID 32548905, 2020). "A phase III trial, KEYNOTE-024, compared pembrolizumab (PD-1 inhibitor) with platinum-doublet chemotherapy in EGFR/ALK-negative, advanced NSCLC patients with tumor positive for PD-L1 ≥ 50%." (PMID 31049758, 2019). "In the other ALK fusion–negative NAT specimens, more EML4 mRNA was expressed at each exon than in the tumor tissues." (PMID 30943926, 2019). "A phase I trial is assessing the pan-TRK, ROS1 and ALK inhibitor entrectinib in paediatric patients with relapsed or refractory solid and Central Nervous System (CNS) tumours with and without TRK, ROS1 and ALK fusions (NCT02650401)." (PMID 29642598, 2018). "In contrast to ALK-positive H3122 tumor cells, addition of TAE684 does not affect the antiproliferative effect of radiotherapy in two other NSCLC lacking ALK-activation." (PMID 29304828, 2018). "Here we investigated pSTAT3 expression by IHC in primary tumor samples from 169 patients samples and found that 27% PTCL-NOS, 29% AITL, and 57% ALCL ALK-negative tumors express pSTAT3." (PMID 30420593, 2018). "Over the next decade, the two provisional entities known as ALK-positive and ALK-negative ALCL were proposed and finally adopted into the WHO classification of tumours of haemopoietic and lymphoid tissues in 2017." (PMID 29601554, 2018). "A liquid biopsy of circulating tumor cells (CTCs) was also performed, and EMT-CTCs positive for vimentin but negative for ALK rearrangement were detected per 7.5 ml blood by FISH." (PMID 29844868, 2018). "IHC was mainly positive for tumor markers like CD10, CD20, CD45, CD 79a, PAX5, MUM1, and BCL6, and negative for BCL2, ALK, CD30, and cyclin D1." (PMID 30764662, 2018). "In our analysis, we found that in adult ALK-negative ALCLs, the expression of granulysin was less strong and intense than in ENKTL cases and in addition restricted to a small proportion of tumour cells (less than 25%; score 1)." (PMID 30151671, 2018). "For case N°4, the ALK status was discordantly assessed by IHC (positive: H-Score 300) and FISH (negative: break apart found in 10% of tumor cells)." (PMID 30326973, 2018). "The two IHC-positive/FISH-BL-positive cases were both positive on the RNA-level, whereas a tumor with questionable IHC and FISH-BL-positive status displayed no ALK fusion transcript." (PMID 30466405, 2018).